MTOR (mechanistic target of rapamycin kinase)
Diseases named in the same sentence as MTOR in open-access papers (continued):
Sharing a sentence is not in itself a finding about the gene and the disease.
pituitary tumor (13 papers, 2011 to 2023). A benign or malignant neoplasm affecting the pituitary gland. "Finally, abnormalities of kinases of the mTOR (mammalian target of rapamycin) pathway have also been linked to pituitary tumor development." (PMID 35260162, 2022). "Innovative targeted therapies for pituitary tumor treatment are focusing on inhibitors of the mammalian target of rapamycin (mTOR), tyrosine kinase, and vascular endothelial growth factor." (PMID 38275385, 2023). "Both the PI3K/Akt/mTOR and Raf/Mek/ERK pathways are upregulated in pituitary tumors and implicated in pituitary tumorigenesis." (PMID 32012988, 2020). "Yao et al46 found that Deptor up‐regulated sensitivity of pituitary tumour cells to cabergoline, decreased its proliferative functions by promoting autophagy via inhibition of mTOR activity." (PMID 32510855, 2020). "Researchers have shown that the combination treatment targeting AMPK and PI3K/Akt/mTOR pathway at the same time in GH-secreting pituitary tumors achieved a better treatment effect than the single medication alone." (PMID 31920959, 2019). "Together, these data suggest, for the first time, a potential role for mTOR inhibitors in the treatment of pituitary tumors, both as a cytostatic agent and as an adjunct to radiation." (PMID 21427787, 2011). "The PI3K/AKT/mTOR pathway has been shown to be overexpressed in both hormonally active and inactive pituitary adenomas compared to normal pituitary, and has also been reported to be upregulated in invasive pituitary tumors." (PMID 38202123, 2023). "mTOR inhibition reduces viability of human pituitary tumor cells in vitro." (PMID 26793165, 2015). "Targeting PI3K/Akt/mTOR signaling is of potential therapeutic interest in human pituitary tumors." (PMID 26793165, 2015). "To date, everolimus (EVE) is the only PI3K/AKT/mTOR pathway inhibitor that has been studied in patients with aggressive pituitary tumors, with a total of seven documented cases (four AgPitNETS and three MetPitNET; three corticotrophs, one lactotroph and three of unknown histology)." (PMID 38202123, 2023). "Therefore, the H19–4E-BP1 axis and the CAB–AKT/mTOR axis may be of great therapeutic potential for targeting human pituitary tumours that are refractory to available therapies or surgical treatment." (PMID 30397197, 2018). "Although we collected all published clinical evidence investigating mTOR and RAF/MEK/ERK pathway expression in pituitary tumors, the number of publications used for the systematic review was relatively small." (PMID 37446128, 2023). "The aim of our study is to determine the role of the activation of PI3K/AKT/mTOR and RAF/MEK/ERK pathways in the pathogenesis of pituitary tumors." (PMID 37446128, 2023). "The aim of our review is to determine the role of the activation of PI3K/AKT/mTOR and RAF/MEK/ERK pathways in the pathogenesis of pituitary tumors." (PMID 37446128, 2023). "CAB induced formation of autophagosome in rat pituitary tumor MMQ and GH3 cells at the early stage through inhibiting mTOR pathway, resulting in higher conversion rates of LC3-I to LC3-II, GFP-LC3 aggregation, and increased autophagosome formation." (PMID 26513171, 2015). "Likewise, in primary cultures of pituitary tumor cells from MENX rats, cell viability is more effectively reduced by the dual PI3K/mTOR inhibitor NVP-BEZ235 than by everolimus alone." (PMID 26793165, 2015). "In rat GH-secreting pituitary tumor GH3 cell lines, rapamycin, its bioavailable analog RAD001 (Everolimus), and PI3K inhibitors have been shown to decrease cell viability and proliferation through inhibition of mTOR activity and interruption of normal cell cycle function." (PMID 32012988, 2020). "These properties potentially limit the clinical usefulness of rapamycin in the management of pituitary tumors; however, more stable and soluble rapamycin analogues, such as RAD001, may retain biological activity against mTOR, and thus, could be more amendable to clinical use." (PMID 21427787, 2011).
schwannoma (13 papers, 2012 to 2025). A benign, usually encapsulated slow growing tumor composed of Schwann cells. "mTOR signaling has also been experimentally demonstrated to be dysregulated in NF2-associated schwannomas, and clinical trials with mTOR inhibitors such as everolimus and sirolimus have shown efficacy in reducing the growth of tumors in NF2 patients." (PMID 31161239, 2020). "In merlin-deficient schwannomas, mammalian target of rapamycin complex 1 (mTORC1) is constitutively activated, and mTOR inhibitors such as rapamycin (sirolimus) and its rapalogs (e.g., everolimus) influence vestibular schwannoma cell proliferation." (PMID 31936793, 2020). "The PI3K/AKT/mTOR pathway governs essential cellular processes—particularly anabolic metabolism, growth, and survival—and is reported to be upregulated in schwannomas." (PMID 41300852, 2025). "Pharmacological suppression of mTOR signaling can diminish schwannoma development in vivo, according to allograft research in mice." (PMID 34824953, 2021). "Merlin-mediated mTOR signaling suppression has been demonstrated to assist Merlin's tumor suppressive action in schwannomas." (PMID 34824953, 2021). "Analysis of molecular pathways in P0-CreC;Smarcb1flox/flox RTs by western blot showed increased phosphorylation of Akt, S6, and 4E-BP1, consistent with activation of the mTOR/Akt pathway, similar to schwannomas in P0-CreC;Nf2flox/flox mice." (PMID 28824165, 2017). "Proposed pathways of tumorigenesis include loss of Merlin-mediated inhibition of the MAP kinase MEK/ERK cascade, abnormalities in the PI3K/mTOR pathway, interactions between vascular endothelial growth factor (VEGF) secreted by schwannoma cells and endothelial cells, and KRIT1 gene mutations." (PMID 40342451, 2025). "Moreover, the therapeutic value of regulating necroptosis via mTOR has also been confirmed in schwannoma." (PMID 38164133, 2023). "The pathways implicated in schwannoma tumorigenesis are the loss of Merlin-mediated inhibition of the MAP kinase MEK/ERK cascade), and the PI3K/mTOR signaling pathways (phosphatidylinostitol-3 kinase (PI3K)/serine-threonine protein kinase/Akt cascade/mTOR/p70S6K)." (PMID 34824953, 2021). "As a result, the lack of Merlin-mediated regulation of mTOR signaling in a schwannoma, as well as the VEGF-A/VEGFR-2 enhanced PI3K/Akt/mTOR pathway in ECs inside a schwannoma, might result in synchronous hemangiomatous development." (PMID 34824953, 2021). "Therefore, in vivo and in vitro, mTORC1 is a critical regulator of schwannoma growth, and mTOR inhibition may open up new opportunities for targeted therapies to stop the growth in these tumors." (PMID 31936793, 2020). "The dual inhibition of the PI3K/AKT/mTOR pathway by inhibitors (BEZ235, PKI-578) has been shown to increase cell death and decreases cell viability in schwannoma cell line models (HEI-293)." (PMID 31936793, 2020). "For non-operative candidates, the combination of an mTOR inhibitor and dasatinib may hold promise for the treatment of schwannomas." (PMID 39958061, 2025).
bladder urothelial carcinoma (12 papers, 2013 to 2025). "Recent study stated that sperm‐associated antigen 5 (SPAG5) activated AKT/mTOR signalling in bladder urothelial carcinoma, indicating SPAG5 might regulate autophagy and play a role in podocyte damage." (PMID 31957155, 2020). "In addition, miR-99a-5p was shown to be a tumor-suppressor miR, by targeting mTOR in human urinary bladder urothelial carcinoma cells and miR-335-5p regulation was associated with tumor proliferation and invasion." (PMID 31947507, 2020). "For example, SPAG5 promoted cell proliferation and reduced cell apoptosis in bladder urothelial carcinoma via regulating Wnt3/AKT/mTOR pathway." (PMID 35138218, 2022). "SPAG5 promotes proliferation and suppresses apoptosis in bladder urothelial carcinoma at least partially via up-regulating Wnt3 by activating the AKT/mTOR signaling pathway." (PMID 31985007, 2020). "Akt-mTOR signaling plays a major role in bladder carcinogenesis, with Akt activation occurring over the entire spectrum of bladder urothelial carcinomas." (PMID 25136960, 2014). "The mechanisms mediated by MIR4435-2HG may include modulation of cell cycle regulator activity and mTOR signaling in the stroma-enriched subtypes of urothelial carcinoma of the bladder." (PMID 37355516, 2023). "In a study performed using cell lines from urothelial bladder cancer (BLCA), a tumour in which 50–70% of cases show activation of the PI3K/AKT/mTOR signalling, the pan-AKT inhibitor MK-2206 decreased cell viability in a number of cell lines." (PMID 40943262, 2025). "It is reasonable to think that the down expression of miR-100 that we previously observed in low-grade, non-invasive bladder urothelial cancer is related to the lack of control of mTOR and FGFR3 and to the maintenance of genomic stability due to not interfering with SMARCA5." (PMID 25493074, 2014).
hepatitis C (12 papers, 2014 to 2025). "However, modifiable risk factors can include perioperative stress, vitamin D deficiency, cytomegalovirus or hepatitis C, and immunosuppressive medications like glucocorticoids, mTOR inhibitors, and calcineurin inhibitors." (PMID 36895529, 2023). "These genes also showed significant enrichment of KEGG pathways associated with mTOR signaling pathway, Fatty acid biosynthesis/metabolism, PI3K-Akt signaling pathway, Influenza A, and Hepatitis C." (PMID 41181322, 2025). "By using the PICRUSt, compared to the p16-negative group, the p16-positive group was significantly enriched for pathways involved in germination, flavone and flavonol biosynthesis, cell cycle, mTOR signaling pathway, and hepatitis C." (PMID 38419008, 2024). "Both human cytomegalovirus and Hepatitis C Virus infection can induce mTOR-independent phosphorylation of 4E-BP1 in PI3K-dependent manner." (PMID 32603377, 2020).
interstitial lung disease (12 papers, 2014 to 2025). A diverse group of lung diseases that affect the lung parenchyma. "Several anti-HER2 therapies, as well as other anticancer agents (e.g., cyclin-dependent kinase-4/-6 inhibitors, immune checkpoint inhibitors, mammalian target of rapamycin [mTOR] inhibitors), have been linked to an increased risk of drug-induced interstitial lung disease (ILD)." (PMID 32591987, 2020). "mTOR, which can form mTOR Complex 1 (mTORC1) or mTOR Complex 2 (mTORC2) depending on its binding partners, is frequently deregulated in the pulmonary neoplastic conditions and interstitial lung diseases of the patients treated with rapalogs." (PMID 24571487, 2014). "However, the problem with long-term therapy with the mTOR inhibitor everolimus is that it reduces the size of tumors but does not cure them, thereby increasing the chances of gonadal dysfunction, interstitial lung disease, and immunosuppression-related complications." (PMID 41194857, 2025). "Interstitial lung disease and nephritis, which are frequently observed during treatment with mTOR inhibitors in solid organ transplant recipients and cancer patients, may be another clues indicating relationship between mTOR pathway and EMT." (PMID 24571487, 2014). "As we discuss above, this association can be explained by the immunosuppressive effect of mTOR inhibitors but without ruling out the possibility of having included mTOR inhibitor-induced interstitial lung disease in some cases." (PMID 38328616, 2024). "Interstitial lung disease (ILD; characterized by the inflammation of the interstitium of the lung) and non-infectious pneumonitis (characterized by the presence of non-infectious, nonmalignant infiltrates) are known side effects of mTOR inhibitors." (PMID 23404211, 2014).
Leigh syndrome (12 papers, 2014 to 2022). A progressive neurological disease defined by specific neuropathological features associating brainstem and basal ganglia lesions. "Johnson and colleagues successfully extended the survival of a mouse model of Leigh syndrome, which was deficient in Ndufs4 of complex I, by chronic administration of the mTOR inhibitor, rapamycin." (PMID 35681427, 2022). "Inhibition of mTOR with rapamycin has been shown to exert beneficial effects on several RC-deficiency models, including models of Leigh syndrome, mtDNA depletion, and renal disease in Pdss2kd/kd mice." (PMID 34349107, 2021). "A causal link between impaired mitochondrial function and mTOR activation has been demonstrated in Leigh syndrome, and it is most likely that it also applies to Esrrg-cKO Tregs." (PMID 34156979, 2021). "A 2 year-old Leigh syndrome patient homozygous for the known pathogenic c.355G > C (pAsp119His) mutation in NDUFS4 responded strikingly well to mTOR inhibition therapy, with a reversal of brain lesions and striking recovery of gross motor function which persisted through ~ 20 months of therapy." (PMID 36056365, 2022). "Perturbations of the glutamine/glutamate/αKG metabolic axis were also found in the Ndufs4 KO mouse model of Leigh syndrome while being rescued by mTOR inhibition with rapamycin." (PMID 35884972, 2022). "In fact, mTOR activity can be stimulated even in the presence of active AMPK, as in the case of the Leigh syndrome caused by mutation in complex I subunit Ndufs449." (PMID 32157127, 2020). "Although investigation into the use of mTOR inhibitors in Leigh syndrome is at a very early stage, preclinical results are promising because there are currently no effective therapies for this disease." (PMID 28288694, 2017). "The mechanism behind this is not entirely understood; however, it is believed that reduction of mTOR activity may shift cell metabolism toward amino acid catabolism and away from glycolysis and, thus, reduce the buildup of glycolytic intermediates that are associated with Leigh syndrome." (PMID 28288694, 2017). "mTOR inhibition by rapamycin has also been shown to provide benefit in models of disease such as the murine model of Leigh Syndrome." (PMID 26257774, 2015). "mTOR proteins can be treated as drug target proteins against Leigh syndrome and other mitochondrial disorders." (PMID 25045657, 2014). "The mTOR proteins can be treated as drug target proteins against Leigh syndrome and other mitochondrial disorders." (PMID 25045657, 2014). "This study aims to investigate the potent lead TCM candidates for mTOR protein inhibitors against Leigh syndrome and other mitochondrial disorders." (PMID 25045657, 2014). "A recent research demonstrates that the inhibition of mammalian target of rapamycin (mTOR) improves survival and health for patients with Leigh syndrome." (PMID 25045657, 2014). "and Vitex negundo L. Hence, we propose the TCM compounds, picrasidine M and acerosin, as potential candidates as lead compounds for further study in drug development process with the mTOR protein against Leigh syndrome and other mitochondrial disorders." (PMID 25045657, 2014). "Rapamycin-induced inhibition of mTOR was shown to improve survival and health in the Ndufs4−/− mouse model of Leigh syndrome, so even small effects on mTOR inhibition could be beneficial in this context." (PMID 33148885, 2020). "A goal of current research is to identify the role of mTOR inhibition in neurologic and developmental disorders beyond that of TSC (e.g., Leigh syndrome, Down syndrome, and neurofibromatosis types 1 and 2), which nonetheless share a common feature of mTOR pathway hyperactivation." (PMID 28288694, 2017). "Additional research has suggested mTOR inhibition may aid in Leigh syndrome through preservation of adenosine triphosphate (ATP)." (PMID 28288694, 2017).
Leigh syndrome (continued). "Pharmacological manipulation of mTOR might alleviate the metabolic effects of ECHS1‐deficiency paralleling the results obtained in other genetic forms of mitochondrial‐related neurodegeneration, including Leigh Syndrome." (PMID 32329585, 2020). "While the importance of mTOR signaling in brain vs. peripheral tissues in aging and Leigh syndrome is not yet known, these reports demonstrate that circulating levels of rapamycin achieved by daily IP injection are sufficient to reduce mTOR signaling in the central nervous system." (PMID 26257774, 2015).
lipid metabolism disorders (12 papers, 2020 to 2025). "The inhibition of the mTOR pathway more significantly exacerbated the lipid accumulation, lipid metabolism disorder, and mitochondrial dynamic balance disruption." (PMID 33479191, 2021). "The previous study showed that high ammonia exposure activated the mTOR-p70s6k pathway, leading to lipid metabolic disorder in skeletal muscle, which might be due to the increment in serums HCA, LCA, and HDCA induced by ammonia exposure in this study." (PMID 34179063, 2021). "Down-regulation of rapamycin-targeted protein (mTOR) phosphorylation and n-SREBP-1c protein levels in high-fat diet (HFD)-fed mice and reduction of lipid accumulation in IR and lipid metabolism disorders through mTOR-dependent pathways." (PMID 38436812, 2024). "Therefore, LXJDF could regulate part of the PI3K/Akt/mTOR pathway, reduce TG and oxLDL, and increase HDL to adjust lipid metabolism disorders." (PMID 33762935, 2021).
lymphatic malformation (12 papers, 2017 to 2025). Primary lymphedema is caused by anatomic or functional defects in the lymphatic system, resulting in chronic swelling of body parts and lymphatic-system malformation. "Sirolimus, a mechanistic target of rapamycin (mTOR) inhibitor, was initiated for refractory chylous ascites associated with lymphatic malformations at 41 days of age." (PMID 39569283, 2024). "On the other hand, the PIK3CA/Akt/mTOR pathway, as PIKopathy, induces slow-flow vascular malformations, such as venous or lymphatic malformations." (PMID 35216474, 2022). "The mTOR inhibitor sirolimus has been found to be effective in lymphatic malformations that were refractory to standard treatment." (PMID 33051716, 2021). "Recently, the therapeutic effects of small compounds on the inhibition of the PI3K/AKT/mTOR signaling pathway for venous malformation, lymphatic malformations (LMs), and PROS with PIK3CA mutants have been reported." (PMID 28525374, 2017). "Abnormal capillary dilation may occur via the same mechanism as indicated for venous or lymphatic malformations through PIK3CA/Akt/mTOR." (PMID 35216474, 2022). "PIK3CA mutations in lymphatic malformation may stimulate the expression of VEGF-C or VEGFR3, induce the binding of PIK3CA to the cellular membrane, or increase cell proliferation, chemotaxis, and angiogenesis through the activation of downstream Akt/mTOR." (PMID 35216474, 2022). "It has been reported to simultaneously inhibit the mTOR and vascular endothelial growth factor (VEGF) pathways in lymphatic malformations, demonstrating efficacy in many cases even those without mTOR activation." (PMID 38201347, 2023). "Chemotherapy, such as sirolimus and alpelisib, inhibitors of the PI3K/AKT/mTOR pathway, has proven effective and safe in a variety of PIK3CA-related vascular anomalies, such as venous/lymphatic malformations (VM/LM) and PROS, by offsetting the progression of the malformations." (PMID 34980271, 2022).